CFAP418-AS1 (CFAP418 antisense RNA 1)
Synonyms: tospeak; C8orf37-AS1
Gene: Long non-coding RNA gene on chromosome 8 (95,204,456 to 95,811,254, forward strand). Ensembl gene ENSG00000253773.
Gene Ontology:
Molecular function: triplet codon-amino acid adaptor activity
Biological process: translation